TK1 (thymidine kinase 1)
Diseases named in the same sentence as TK1 in open-access papers (continued):
Sharing a sentence is not in itself a finding about the gene and the disease.
tumor (continued). "The reported sensitivity of TK1 as a tumour marker depends on the assay and corresponding cut‐off value and lies between 71% and 74%." (PMID 36495211, 2023). "Results of spatial transcriptome analysis showed that TK1 positive cells mainly localize in tumor area, and Treg cell infiltration in TNBC tissues was associated with high expression of TK1." (PMID 37767092, 2023). "In this study, serum TK1 correlated with tumor growth rate and was also a prognostic biomarker for death at the follow-up." (PMID 37373974, 2023). "High TK1 activity correlates with worse performance status, more advanced tumor stage and higher levels of LDH, another enzyme that leaks out of cancer cells." (PMID 37377898, 2023). "Our work revealed the underestimable potential of TK1 as a tumor biomarker and immunotherapeutic target." (PMID 37767092, 2023). "Our analysis showed that TK1 expression in patient tissue samples across multiple cancer types was significantly higher in tumor samples as compared to healthy tissues." (PMID 38033034, 2023). "In terms of prognostic interest, it has been shown that the activity of TK1 increased with tumour stage." (PMID 35815441, 2022). "At present, some potentially predictive biomarkers have been found for CDK4/6 inhibitors, such as cyclin E1 (CCNE1), thymidine kinase 1 (TK1) mRNA expression, and circulating tumour DNA (ctDNA)." (PMID 36028895, 2022). "Several prior studies have shown that the transcription factor E2F1 can directly regulate TK1 and promote tumor proliferation." (PMID 36035114, 2022). "TK1 expression was analysed in archival tissue samples of 110 patients with 146 tissue samples, including 93 primary tumour, 51 metastatic, and 2 recurrence tissue samples." (PMID 36291880, 2022). "[18F]FLT imaging in conjunction with a specific inhibitor of G1/S that rapidly down regulates TK1 and depletes S phase provides an in vivo measure of on target effect prior to measurable tumor volume change." (PMID 35982453, 2022). "TK1 ablation inhibited tumor cell proliferation and migration potential, and in vivo experiments showed that TK1 inactivation can significantly restrain tumor growth." (PMID 35559045, 2022). "This possibility requires further investigation using in vitro and in vivo models to assess TK1 and the possible biological mechanisms of tumor immune crosstalk in PCa." (PMID 36035114, 2022). "A similar trend was seen when analysing only metastatic tissue samples, although the result was significant at a higher TK1 cut-off value (15% for percentage TK1-expressing tumour cells)." (PMID 36291880, 2022). "In all patients, the TK1 expression levels were significantly higher in primary tumour tissue samples compared to recurrent or metastatic tissue samples (Kruskal–Wallis test, p < 0.05)." (PMID 36291880, 2022). "From its early beginnings, studies involving TK1 have been focused mainly on its use as a tumor biomarker." (PMID 35239730, 2022). "As TK1 levels in serum are correlated with tumor progression, patient response and cancer recurrence, TK1 has also been proposed as a suitable tumor biomarker for the continued monitoring of patients." (PMID 35239730, 2022). "Tumor accumulation of [18F]FLT strongly correlates with TK1 activity and percentage of cells in S phase." (PMID 35982453, 2022). "In this study we isolated human antibody fragments against the tumor proliferation biomarker TK1 from a sdAb library." (PMID 35239730, 2022). "The expression of marker genes of C6 cluster cells, including a total of 276 genes such as TOP2A, MKI67, and TK1, was higher in tumor tissues than in normal tissues from TCGA database." (PMID 36046337, 2022). "Most importantly, GO analysis revealed that TK1 expression was related to several important oncogenic/tumor suppressor pathways, including DNA repair (75.5%, p = 2.5e-14), apoptosis (53.7%, p = 0.03), and cell cycle (70.9%, p = 8.3e-22)." (PMID 35311151, 2022).
tumor (continued). "Using TIMER, the correlation between the TK1 copy number and tumor-infiltrating lymphocytes (TILs) was investigated." (PMID 35559045, 2022). "Interactive analysis of the gene expression profiles also verified that TK1 levels were higher in PCa tumor tissues than in paraneoplastic tissues." (PMID 36035114, 2022). "Posttreatment pathology specimens were assessed for tumor necrosis or fibrosis and for Ki-67 and thymidine kinase 1 expression." (PMID 34593596, 2022). "While the usefulness of TK1 as a tumor biomarker has been the main focus of many studies, in recent years the interest in using TK1 as a therapeutic target for multiple cancers has gradually increased." (PMID 35239730, 2022). "The dynamics during treatment are also more pronounced in DLBCL, where the majority of tumor cells would display an unregulated TK1 expression." (PMID 34471484, 2021). "Thymidine kinase 1 is upregulated during rapid cell proliferation and serum activity of this enzyme correlates with levels of cell proliferation within neoplasms." (PMID 34359096, 2021). "As in the previous study, the association of the sTK1 reaction to chemotherapy with survival points to the tumor specificity of TK1." (PMID 34771604, 2021). "The [18F]FLT tumor uptake depends on thymidine kinase 1 (TK1) activity, including therapy-induced activation of the salvage pathway and expression of nucleoside transporters." (PMID 34988446, 2021). "Expression of TK1 was categorized as high with a cut-off of 15% based on the percentage of tumor cells staining positive for TK1 with a score of 2+ or 3+." (PMID 34884270, 2021). "Controversially, MCs in EC can both promote tumor cell growth through TK1/mitogenic kinin signaling and exert anti-tumor effects, through activation of CD169+ TAMs and CD8+ effector cells." (PMID 33995371, 2021). "Up-regulation of TK1 can promote angiogenesis and invasion by lung cancer cells, thereby accelerating tumor progression." (PMID 35127491, 2021). "Tissue kallikrein (TK1), which is highly expressed in activated mast cells, can participate in the formation of mitogenic kinin, which can stimulate the proliferation of tumor cells and enhance metastasis by increasing vascular permeability." (PMID 33541291, 2021). "The principle of 18F-FLT is based on phosphorylation of the fluorinated thymidine analog by the enzyme thymidine kinase 1 (TK1) and its consecutive entrapment within the tumor cell." (PMID 33926002, 2021). "In search of possibilities to recognize resistance, various circulating biomarkers such as tumor DNA, RNA, exosomes, circulating tumor cells and thymidine kinase 1 (TK1) have been evaluated." (PMID 34771604, 2021). "TK1 expression levels in the tumor were evaluated by immunohistochemistry in a pooled analysis of 329 patients participating in the J-003 trial and patients recruited from Japan in the RECOURSE trial." (PMID 34884270, 2021). "The mice were subcutaneously injected with ESC410 cells transfected with oe-NC + sh-NC, oe-CCAT2 + sh-NC, or oe-CCAT2 + sh-TK1, and their tumor volume measured every week." (PMID 34386421, 2021). "In patients with different tumor types, TK1 activity has been shown to carry prognostic information and potential in tumor monitoring." (PMID 32161278, 2020). "Although the role of TK1 as a tumor biomarker has extensively been studied, little has been done to explore the potential of TK1 as tumor target." (PMID 32317865, 2020). "Previous findings confirming the presence of cell membrane associated TK1 forms in tumor cells from patients, and recent studies reporting the targeting of TK1 expression inside cells have strengthened the clinical relevance of TK1 as a tumor target." (PMID 32317865, 2020). "The antibodies developed showed potential to be used to detect and target TK1 on the membrane of various tumor cells." (PMID 32317865, 2020).
tumor (continued). "When evaluating TK1 as a tumor biomarker in comparison with other validated markers, researchers have found that TK1 possesses significant advantages in comparison to such biomarkers as Ki-67." (PMID 33292474, 2020). "Across many cancer types, serum TK1 has shown effectiveness as a tumor biomarker and, in some cases, to possess advantages in comparison to other biomarkers." (PMID 33292474, 2020). "Scientific evidence suggests TK1 is a suitable tumor biomarker for the early detection of malignancy, tumor progression, prediction of recurrence and patient outcome." (PMID 32317865, 2020). "Serum TK1 levels were significantly higher in CRC than in healthy controls (p<0.05) and showed significant associations with tumor stage, histopathological grade, lymph node status and metastasis (p<0.01)." (PMID 33247667, 2020). "TK1 levels showed a positive correlation with tumor stage, grade, lymph node involvement and presence of metastasis." (PMID 33247667, 2020). "Despite the large number of studies demonstrating the value of TK1 as a cancer biomarker and its potential as a tumor target, there are a limited number of clinically tested antibodies for the detection and targeting of TK1." (PMID 32317865, 2020). "While TK1 has been well established as a tumor biomarker, little has been done to explore its potential as a tumor target." (PMID 32317865, 2020). "Sandwich Elisa, biotin-labeled antibody kit was used for TK1, and other tumor markers were measured using electro-chemiluminescence." (PMID 33247667, 2020). "The TK1 is closely related to the process of angiogenesis, tumor proliferation, differentiation, invasion and metastasis of many tumors." (PMID 32202305, 2020). "Serum TK1, in our study, showed significant correlation with tumor’s clinicopathological stage and differentiation." (PMID 33247667, 2020). "The effects of TK1 knockdown on the in vivo tumor growth of TPC-1 were evaluated in nude mice xenografts model." (PMID 32064235, 2019). "Collectively, these results demonstrate that TK1 promotes LUAD tumor growth, in part, by stimulating the expression of GDF15." (PMID 31589613, 2019). "Collectively, these results demonstrate that inhibition of TK1 blocks tumor growth and metastatic attributes of LUAD cells, both in cell culture and in mice." (PMID 31589613, 2019). "Here, we found that GDF15 is an important mediator of TK1 function, as the TK1 knockdown-induced reduction in LUAD tumor growth and metastasis can be rescued by ectopic expression of GDF15." (PMID 31589613, 2019). "This suggests that the ability of TK1 to promote tumor growth and metastatic attributes of LUAD cells occurs independently of its role in the regulation of DNA damage." (PMID 31589613, 2019). "Biomarkers that indicate tumor proliferation rate, such as thymidine kinase 1 (TK1), can be determined in tumor tissue (tTK1, immunohistochemistry) and in body fluids, such as serum (STK1)." (PMID 31878191, 2019). "Based on these results, we next asked if TK1 knockdown inhibits LUAD tumor growth and metastasis in vivo." (PMID 31589613, 2019). "To this end, we first tested the effect of TK1 knockdown on LUAD tumor growth, using two sequence-independent short hairpin RNAs (shRNAs) to target TK1 in three different LUAD cell lines (A549, H1299 and H460)." (PMID 31589613, 2019). "We knocked down TK1 expression using shRNA and performed a series of cell culture and mouse-based studies to assess the effect on knockdown on tumor growth and metastasis." (PMID 31589613, 2019). "[18F]Fluorothymidine ([18F]FLT) is the leader of fluorinated thymidine PET tracer, which tumor uptake is directly related to the thymidine kinase 1 (TK1) activity." (PMID 31832803, 2019). "Our results show that knockdown of TK1 significantly inhibits tumor and metastatic growth, both in cell culture and in mice, suggesting that TK1 expression is required for tumor growth and the metastatic attributes of LUAD cells." (PMID 31589613, 2019).
tumor (continued). "To confirm this result, we further analyzed the expression of thymidine kinase 1 (TK-1) or CD44 isoforms in our system, as TK-1 is known to be a tumor proliferation marker, and ESRP1 is known to regulate CD44 isoform switching during the EMT." (PMID 31362365, 2019). "Taken together, these results provide an important validation for the proposed role of TK1 as a facilitator of LUAD tumor and metastatic growth." (PMID 31589613, 2019). "Consistent with the results of the cell culture experiments, TK1 knockdown led to significant inhibition of tumor growth in vivo for all the LUAD cell lines tested." (PMID 31589613, 2019). "We further show that knockdown of TK1 inhibits tumor growth and metastatic attributes by inhibiting Rho GTPase activity and by reducing the expression of growth and differentiation factor 15 (GDF15)." (PMID 31589613, 2019). "The quantitative real-time PCR analysis showed that TK1 was downregulated in the tumor tissues from the sh_TK1 group when compared to the sh_NC group." (PMID 32064235, 2019). "Collectively, our findings demonstrate that TK1 facilitates LUAD tumor and metastatic growth and represents a target for LUAD therapy." (PMID 31589613, 2019). "TK1 knockdown reduced the tumor volume in the nude mice; consistently, the weight of dissected tumor tissue was significantly lower in the h_TK1 group when compared to the sh_NC group." (PMID 32064235, 2019). "To further characterize TK1’s potential as a tumor biomarker, we evaluate TK1 as a potential immunotherapeutic target." (PMID 30214377, 2018). "Analysis of Ki-67 staining demonstrated that proliferation had halted by day 3 after the start of cetuximab monotherapy in the drug-sensitive model, with a concomitant reduction in TK1 and tumor thymidine." (PMID 29794225, 2018). "In this study, we further characterized TK1’s potential as a tumor biomarker and immunotherapeutic target and clinical relevance." (PMID 30214377, 2018). "Tumour uptake of 18F-FLT was shown to be well correlated with proliferation kinetics owing to the fact that the activity of TK-1 is elevated during the S phase." (PMID 30149561, 2018). "They reported that their complex was able to successfully hinder TK1 protein and TK1 mRNA prevalence in vitro and reduce tumor growth by 250% when compared to a control for an in vivo mouse model." (PMID 30539365, 2018). "Thymidine kinase 1 (TK1) is a nucleotide salvage pathway enzyme involved in cellular proliferation and considered an important tumor proliferation biomarker in the serum." (PMID 30214377, 2018). "Thymidine kinase 1 (TK1) is a nucleotide salvage pathway enzyme involved in cellular proliferation and considered an important tumor proliferation biomarker." (PMID 30214377, 2018). "PET studies with radiolabelled sigma-2 receptor ligands supplied superior tumour specific information compared to thymidine kinase-1 based radiotracer imaging." (PMID 30149561, 2018). "There was high concordance, at 89.8% (95% CI: 79.2% - 96.2%), between changes in serum TK1 and tumor Ki-67 in the same direction from C1D1 to C1D15 and from C1D15 to surgery time points." (PMID 29162134, 2017). "Serum TK1 activity was determined at baseline, C1D1, C1D15, and time of surgery, and we found that it was correlated with tumor Ki-67 and TK1 messenger RNA (mRNA) levels." (PMID 29162134, 2017). "Upon internalization, [18F]FLT is phosphorylated by thymidine kinase (TK1) and consequently trapped in the tumor cell." (PMID 27798786, 2017). "The sensitivity and specificity for the tumor Ki-67-based response by palbociclib-induced decrease in serum TK1 were 94.1% (95% CI 86.2% - 100%) and 84% (95% CI 69.6% -98.4%), respectively." (PMID 29162134, 2017). "This study demonstrates that serum TK1 activity was significantly reduced after 2 weeks of treatment with palbociclib, and that changes in serum TK1 significantly correlated to changes in tumor Ki-67 proliferation index and tumor TK1 mRNA levels." (PMID 29162134, 2017).
tumor (continued). "Tumor avidity for FLT is well correlated with TK1 expression and activity, the rate-limiting step in the thymidine salvage pathway, and with the cell surface expression of ENT1." (PMID 27655645, 2017). "The TS and TK1 staining proved the pronounced enzyme expression in the IGR37 xenograft tumor tissue." (PMID 28608446, 2017). "We examined the drug-induced change in serum TK1 as well as its correlation with change in tumor Ki-67 levels in patients enrolled in the NeoPalAna trial (ClinicalTrials.gov identifier NCT01723774)." (PMID 29162134, 2017). "The TK1 protein levels increased more clearly but overall followed a similar pattern with regard to tumor stage." (PMID 27079872, 2016). "Proliferation in tumor cells correlates with high levels of TK1 since this enzyme plays an important role in pyrimidine deoxynucleotide synthesis." (PMID 27079872, 2016). "The development of anti-human TK1 antibodies has extended the application of serum TK1 protein determination for many different tumor diseases, and several clinical studies have demonstrated increased serum TK1 protein levels in solid-tumor diseases." (PMID 25881026, 2015). "Serum TK1 activity measurement has been used as tumor proliferation marker for the diagnosis and prognosis of various hematological malignancies and in some solid-tumor diseases." (PMID 25881026, 2015). "The STK1 activity levels in these tumor groups were compared using the cut-off values based on TK1 activity in healthy sera." (PMID 26366881, 2015). "In contrast, TYMP and TK1 positive staining were overwhelmingly observed in the tumor tissues, suggesting that Bel-7402 cell line indeed represented such a subtype of liver tumors." (PMID 25881156, 2015). "Normal human liver tissue showed only low basal levels of TYMP and TK1 protein expression as compared to those of tumor samples (panel A versus B)." (PMID 25881156, 2015). "All cancer cell lines had consistently high TK1 expression as compared to the normal liver derived HL-7702 cell line, which was validated by IHC on human normal liver versus tumor samples, supported TK1 as a tumor-specific target." (PMID 25881156, 2015). "Cellular TK1 isolated from ALL tumor cells was predominantly a dimer, while the serum TK1 activity eluted as a high molecular weight (MW) oligomer." (PMID 25293656, 2014). "In this study, we have attempted to determine total tumor TK1 protein and activity levels as well as sTK1 levels in ALL and CMT dogs, using the same methods." (PMID 25293656, 2014). "TK1 is a key enzyme in the salvage synthesis pathway of DNA and TK1 activity in malignant tumour cells is 3–10-fold higher than in benign cells." (PMID 24944599, 2014). "The percentage of patients with better survival in the advanced tumor group was 54.5%, based on the cytoplasmic/nuclear TK1 LI." (PMID 23693054, 2013). "18F-fluorothymidine (18F-FLT) positron emission tomography (PET), which reflects thymidine kinase-1 (TK-1) activity, is a non-invasive method for detecting tumor proliferation." (PMID 24137387, 2013). "COX multivariate hazard analysis also shows that the expression of TK1 in the nuclei of tumor cells is a markedly independent prognostic factor for both CIN III and invasive cervical carcinoma patients, while Ki-67 was not." (PMID 23693054, 2013). "FLT-MP accumulation in xenograft tumors was shown to be sensitive to Docetaxel treatment, and TK1 immunoreactivity co-localized with tumor-specific antigens in xenograft tumors, supporting a role for xenograft-derived TK1 activity in tumor FLT metabolism." (PMID 24280026, 2013). "Nuclear TK1 expression in tumor cells of cervical lesions is an independent prognostic factor, and is important for the judgment of the prognosis of CIN patients, and invasive cervical carcinoma patients." (PMID 23693054, 2013). "Recently a cell cycle–dependent marker, thymidine kinase 1 (TK1), has been introduced to evaluate tumor proliferation by immunohistochemistry." (PMID 23693054, 2013).